AGO3 (argonaute RISC catalytic component 3)
Diseases named in the same sentence as AGO3 in open-access papers:
AGO3 is named in the same sentence as 28 diseases in open-access papers, as found by Europe PMC text mining. Sharing a sentence is not in itself a finding about the gene and the disease. The quoted sentences say what the papers report.
viral infections (5 papers, 2019 to 2025). "Under these conditons, we also observed the nuclear translocation of AGO1 and AGO3 proteins upon viral infection, suggesting that the nuclear accumulation of RNAi factors is a general phenomenon during IAV infection." (PMID 40219968, 2025). "We observed that the two lepidopteran PIWIs, namely Siwi and Ago3, affect the outcome of viral infections in the cabbage looper High Five cells and in the silk moth BmN4 cells." (PMID 35891422, 2022). "During this process, Piwi-5 and Ago-3 became the main factors for the production of vpiRNAs during viral infections even if the role in antiviral defense remains unclear." (PMID 31354527, 2019). "The diversification of Piwi-related factors in Ae. aegypti mosquitoes likely reflects their specialization in the control of different classes of parasitic nucleic acids (mainly transposons), with Piwi-5 and Ago-3 involved more specifically in production of piRNAs during viral infections." (PMID 31354527, 2019). "In this study, we investigated the roles of DCL2, DCL4, AGO2, AGO3 and RDR6 in tomato responses to viral infection." (PMID 33032637, 2020). "Additional examples were Apoptosis inhibitory protein 5 (API5), which binds RNA/mRNA, and is involved in programmed cell death regulation; and protein Argonaute 3 (AGO3), which binds nucleic acids, and provides RNA silencing and defense responses to viral infections." (PMID 35822794, 2021).
developmental delay (4 papers, 2016 to 2025). "Microdeletions of the chromosomal region encoding AGO1 and AGO3 genes were found in five patients with hypotonia, poor feeding, and developmental delay, suggesting the possibility that AGO1 and AGO3 are involved in neurocognitive deficits." (PMID 35736234, 2022). "The AGO1 (OMIM 606228) and AGO3 (OMIM 607355) genes when deleted have been hypothesized to be associated with developmental delays, hypotonia, and poor feeding." (PMID 29726122, 2018). "All three had a history of motor and speech delays of unknown severity; however their deletions also included the AGO1 and AGO3 genes which have been hypothesized to be associated with developmental delays, hypotonia, and poor feeding." (PMID 29726122, 2018). "More precisely, GLUT1 deficiency may cause a specific syndrome which correlates with hyperactivity and developmental delay, RIMS3 is considered to be a novel candidate for autism, GRIK3 has also been associated with developmental delay, and AGO1/AGO3 may be responsible for neurocognitive deficits." (PMID 27713767, 2016).
breast carcinoma (2 papers, 2015 to 2023). "Conversely, AGO3 was consistently found to be associated with AGO2 in the nucleus of the human breast cancer cell line T47D." (PMID 38133208, 2023). "There are four argounatue (AGO) proteins in humans AGO1–4 and evaluation of alterations in AGO1–4 gene expression across breast cancer cell lines and tumor samples has shown that AGO2 is increased in ER− samples versus ER+ while there is no change in AGO1, AGO3, or AGO4." (PMID 26062653, 2015).
adult T cell Leukemia (1 paper, 2023). "Interestingly, the authors measured DROSHA, DGCR8, XPO5, DICER1, AGO2, and AGO3 mRNA expression, and only DICER1 mRNA was differently expressed in CD8+ T-cell–depleted PBMCs from HTLV-1 asymptomatic carriers when compared to patients with acute adult T cell Leukemia." (PMID 37243263, 2023).
autism spectrum disorder (1 paper, 2020). A spectrum of developmental disorders that includes autism, and Asperger syndrome. "Recent SFARI study has identified missense mutations in miRISC proteins AGO1, TNRC6B, and CNOT3 among patients diagnosed with Autism Spectrum Disorders Patients with microdeletions of chromosomal region 1p34.3 encompassing the AGO1 and AGO3 genes also show several neurodevelopmental defects." (PMID 32118035, 2020).
Cirrhosis (1 paper, 2024). A chronic disorder of the liver in which liver tissue becomes scarred and is partially replaced by regenerative nodules and fibrotic tissue resulting in loss of liver function. "AGO2-Abs notably increased in cirrhosis, decompensation, and further in ACLF, unlike AGO1-Abs and AGO3-Abs." (PMID 39119295, 2024).
endothelial dysfunction (1 paper, 2025). In vascular diseases, endothelial dysfunction is a systemic pathological state of the endothelium (the inner lining of blood vessels) and can be broadly defined as an imbalance between vasodilating and vasoconstricting substances produced by (or acting on) the endothelium. "AGO2 and AGO4 are likely to participate in the endothelial dysfunction of children with KD, with AGO4 potentially playing a key role, while AGO1 and AGO3 appear not to participate." (PMID 39857904, 2025). "Our findings suggest that AGO2 and AGO4 are involved in inducing endothelial dysfunction in KD, but AGO1 and AGO3 are not." (PMID 39857904, 2025).
gastric cancer (1 paper, 2016). A primary or metastatic malignant neoplasm involving the stomach. "Knockdown of AGO1, but not of Argonaute 2 (AGO2), Argonaute 3 (AGO3) or Argonaute 4 (AGO4), abolished the miR-558-facilitated protein and transcriptional levels of HPSE in gastric cancer cells." (PMID 27685626, 2016).
Infertility (1 paper, 2023). "However, mutant flies of the other two PIWI proteins, Aubergine (Aub) and Argonaute3 (Ago3), show no apparent phenotype except for infertility, blurring the importance of the piRNA pathway in non-gonadal somatic tissues." (PMID 37733654, 2023).
lung carcinoma (1 paper, 2025). "Transcriptomic analysis revealed that the AGO3 gene contributes to lung cancer brain metastasis by negatively regulating hormone metabolic processes." (PMID 40696604, 2025). "This study identifies AGO3 as a potential biomarker and therapeutic target for lung cancer brain metastasis." (PMID 40696604, 2025). "A LASSO regression model was constructed using the expression matrix of H1975 and H1975-BM51 cells, identifying AGO3, NCSTN, and PGK1 as hub genes associated with lung cancer BM." (PMID 40696604, 2025). "AGO3 mediates lung cancer BM through the negative regulation of hormone metabolic processes, offering new insights and potential therapeutic targets for treating lung cancer BM." (PMID 40696604, 2025). "Comparison of hub genes with DEGs showed that AGO3 expression was significantly upregulated in lung cancer BM and positively correlated with its occurrence." (PMID 40696604, 2025). "Transcriptome sequencing data from H1975 and H1975-BM51 cells were analyzed using LASSO regression to construct a lung cancer-BM model, identifying AGO3, NCSTN, and PGK1 as hub genes." (PMID 40696604, 2025).
melanoma (1 paper, 2016). A malignant, usually aggressive tumor composed of atypical, neoplastic melanocytes. "Next, we determined the mRNA expression of AGO1, AGO2, AGO3 and AGO4 in different melanoma cell lines derived from primary tumors and metastases and in non-melanoma tumor cell lines." (PMID 27518285, 2016).
neuroectodermal tumors (1 paper, 2022). "Three human argonaute genes, argonaute RISC catalytic component 3 (AGO3), AGO1, and AGO4, are often deleted in Wilms tumors of the kidney and have even been linked to neuroectodermal tumors." (PMID 36071981, 2022).
osteoporosis (1 paper, 2025). A condition of reduced bone mass, with decreased cortical thickness and a decrease in the number and size of the trabeculae of cancellous bone (but normal chemical composition), resulting in increased fracture incidence. "The associations among SOCS1, AGO3, and the JAK2/STAT3 signaling pathway in osteoporosis progression were then evaluated." (PMID 41043430, 2025).
ovarian carcinoma (1 paper, 2021). A malignant neoplasm originating from the surface ovarian epithelium. "In addition, differential expression of DICER1, AGO3, and AGO4 was reported in the estrogen-dependent development of the chicken female reproductive tract and hen’s ovarian cancer, suggesting that the sex-steroid hormones play an essential role in the biosynthesis of miRNAs." (PMID 33477993, 2021).
prostate tumour (1 paper, 2023). "We checked the expression levels of CDK6, TNRC6B, AGO1, AGO3, and TNRC6A in PCa tissues, based on data from 465 prostate tumour samples obtained from TCGA-PRAD database, and stratified according to the 2014 ISUP-GG into low-risk (ISUP I and II) and high-risk (ISUP III, IV, and V)." (PMID 37978493, 2023).
ZIKV infection (1 paper, 2019). "Similarly, ZIKV infection in HepG2 cells led to a decrease in DGCR8, Ago1, and Ago3 expression." (PMID 30781519, 2019).
infection (20 papers, 2011 to 2026). The state of being infected such as from the introduction of a foreign agent such as serum, vaccine, antigenic substance or organism. "In the case of infection of Aag2 cells with Sindbis virus (Alphavirus), knockdown of individual Piwi proteins by RNAi showed that Piwi5 and Ago3 represent the main Piwi proteins that process viral genomes/antigenomes into 25–30 nt vpiRNAs." (PMID 36835756, 2023). "At 48 h post-infection, elevated CrPV RNA levels were observed when Siwi or Ago3 were downregulated." (PMID 35891422, 2022). "In fact, accentuated lower CrPV RNA levels, measured by qRT-PCR, were observed when either Siwi or Ago3 were overexpressed, both at 36 h and 60 h post-infection." (PMID 35891422, 2022). "AGO3 plays an important role in RNA silencing and functions upon infection of N. benthamiana with potato spindle tuber viroid (PSTVd), and ABA exposure leads to AGO3-mediated resistance to BaMV infection." (PMID 33630970, 2021). "Ago3 and Piwi5 are the sole Piwi-family proteins required for the production of vpiRNAs during infection of Aag2 cells with Sindbis virus." (PMID 32994324, 2020). "The necrotic symptoms observed in the PVX-infected hpAGO2.3 plants suggest that AGO2, AGO3 or both are also distinctly involved in tolerance to infection with PVX." (PMID 33032637, 2020). "In Aag2 cells, Piwi5 and Ago3 are the primary Piwi-family Argonaute proteins required for biogenesis of vpiRNAs upon infection with Sindbis virus." (PMID 32994324, 2020). "Four days post infection (dpi), the expression of Ago3, Piwi1/3, Piwi6 and Piwi7 was between 4 to 10 folds higher than that of Piwi2, Piwi4 and Piwi5, which nevertheless were upregulated with respect to ovaries of sugar- and blood-fed mosquitoes." (PMID 31790401, 2019). "This somatic piRNA pathway generates piRNAs from viral RNA during infection with cytoplasmic RNA viruses through ping-pong amplification by the PIWI proteins Ago3 and Piwi5." (PMID 30566680, 2019). "Production of vpiRNAs is dependent on Piwi5 and Ago3 during infection of Aag2 cells with the Alphavirus CHIKV, Sindbis and Semliki Forest (SF) viruses, but relies also on Piwi6 following infection with the Flavivirus DENV2." (PMID 31790401, 2019). "Possible proviral functions of ago-2 and ago-3 were also revealed during infections with ZIKV in Aag-2 cells." (PMID 31354527, 2019). "Moreover, the infection of C6-L cells with SINV at an MOI of 1 for 48 h remained intact after the silencing of Ago3." (PMID 37764943, 2023). "Interestingly, the Piwi proteins Aub and Ago3 have recently been shown to have a proviral role during the infection of BmNPV (Baculoviridae) in silkworm larvae (discussed in Section 4.4;)." (PMID 36835756, 2023). "Therefore, individual Siwi and Ago3 knockdowns were induced followed by infection with the CrPV and measurement of the viral RNA levels by qRT-PCR." (PMID 35891422, 2022). "At 24 h post-infection, elevated viral RNA levels were observed when Ago3 was downregulated." (PMID 35891422, 2022). "Interestingly, proviral functions of ago-3 and piwi-6 were revealed for infections with mosquito-specific BUNV and of piwi-5 for (midge-specific) SBV infections." (PMID 31354527, 2019). "We show that RVFV cannot be targeted by artificially induced siRNAs only and that infection produces virus-derived small RNAs with antiviral activity, that Ago2, Piwi4, and Ago3 are involved in the antiviral response, and that RVFV is unable to inhibit at least dsRNA-induced RNAi." (PMID 28497117, 2017). "Additionally, VpHV1-γ infection upregulated key components of RNA silencing (AGO3 and DCL2)." (PMID 41562596, 2026). "However, E/V infection robustly potentiated the transcription of the RNAi pathway components, including Dcr-2 in the siRNA pathway, AGO3 in the piRNA pathway, and Drosha, Dcr-1, and AGO1 in the miRNA pathway, while E/C infection exerted little effect on the RNAi pathways." (PMID 36511715, 2023).
infection (continued). "Additionally, our expression analysis is consistent with a generalist antiviral role for Piwi5, which is elicited both during DENV and CHIKV infection, but suggest a more prominent role for Piwi6 and Piwi1/3 or Piwi4 and Ago3 during infection with DENV and CHIKV, respectively." (PMID 31790401, 2019). "In the comparison of VEEV and E/V, despite the enhanced transcriptions of AGO3, Drosha, Dcr-1, and AGO1, the corresponding fold change values after VEEV infection were significantly lower than those induced by E/V infection." (PMID 36511715, 2023). "Correspondingly, 23% of the infection-induced fungal sRNAs started with C, binding preferentially to AGO5 in Arabidopsis, and 16.7% started with A, binding preferentially to AGO2 and AGO3 in Arabidopsis." (PMID 31969895, 2019). "During infection with Sindbis virus (SINV), the production of piRNAs of viral origin is almost exclusively dependent on ping-pong amplification by Piwi5 and Ago3, whereas the biogenesis of transposon-derived piRNAs is more versatile and involves additional members of the PIWI protein family." (PMID 26068474, 2015). "Whereas AGO1 had transcript levels nearly as high as the housekeeping gene WS41, AGO3 exhibited much lower levels, and in fact transcripts could not be detected at the 3 hours post infection (hpi) or 6 hpi treatments." (PMID 30555430, 2018). "Instead, E/C infection inhibited PIWI4 and PIWI6 productions to approximately 0.6-fold, regardless of a slight increase in AGO3 production." (PMID 36511715, 2023). "Interestingly, Ago2, Ago3 and Piwi 6 silencing resulted in a significant decrease of DENV-1 replication during single infection, but this was not the case in the DENV+ZIKV co-infected cells." (PMID 37440582, 2023). "We found that Ven interacts with Ago3, but not Piwi5, regardless of an ongoing SINV-infection." (PMID 30566680, 2019).
tumor (8 papers, 2007 to 2025). "The strong correlation between the mRNA level of PUS10 and that of established microRNA biogenesis-associated proteins, such as DICER, DGCR8, AGO1 and AGO3, in KIRC tumor tissues hinted at the involvement of PUS10 in microRNA processing." (PMID 37596681, 2023). "Similar interactions between Klp10A and piRNA pathway components (Vasa, Piwi, Aub, Ago3) were observed when extracts from SG tumor was used (nos>dpp,), suggesting that the Klp10A interaction with piRNA pathway components is not unique to GSCs." (PMID 32168327, 2020). "As we found many changes in miRNA expression across the five clinical tumor subtypes we had defined above, we asked whether DICER1, DROSHA, DGCR8, AGO1, AGO2, AGO3 or AGO4 expression differs among these subgroups." (PMID 17922911, 2007).
cancer (5 papers, 2009 to 2025). A tumor composed of atypical neoplastic, often pleomorphic cells that invade other tissues. "By way of example, AGO3 could increase the risk of multiple types of cancer while playing a protective role in only KIRC." (PMID 35911954, 2022). "Here we show that Ago 1 and Ago3 participate in miRNA-mediated de novo DNA methylation in human cancer cells, further implicating both the miRNA machinery and the chromatin remodelling complexes in RNA directed transcriptional gene silencing." (PMID 19232136, 2009).
AGO3 also shares sentences with these, for which no sentence is quoted: Alzheimer disease (2 papers); colon cancer (1); Intellectual disability (1); ischemia (1); late-onset Alzheimers disease (1); liver cirrhosis (1); oral cancer (1); Pheochromocytoma and Paraganglioma (1); Wilms tumors of the kidney (1).